KIF2C (kinesin family member 2C)
Diseases named in the same sentence as KIF2C in open-access papers (continued):
Sharing a sentence is not in itself a finding about the gene and the disease.
tumor (80 papers, 2007 to 2025). "Leveraging the ssGSEA and ESTIMATE algorithms, we observed that high KIF2C expression was associated with reduced infiltration levels of immune and stromal cells, suggesting an immune‐depleted tumor microenvironment." (PMID 40292920, 2025). "Leveraging GSE42352 and GSE33383 and using the ESTIMATE algorithm, we quantified the association between KIF2C expression levels and immune and stromal scores, as well as tumor purity in OS." (PMID 40292920, 2025). "High expression levels of KIF2C were commonly associated with tumor malignancy and poor patient outcomes." (PMID 40835789, 2025). "Subsequent single‐cell sequencing revealed that KIF2C was predominantly expressed in CD8 Tex (i.e., T cell exhaustion) cells, indicative of an association between KIF2C and immune exhaustion in the OS tumor microenvironment." (PMID 40292920, 2025). "In line with a deregulated cytokine secretion, KIF2C expression was also associated with a relative abundance of tumor-infiltrating lymphocytes (TILs) and CD4+ T cells in PAAD patients." (PMID 38344808, 2024). "In tumor immunity, KIF2C was significantly associated with CAFs, TAMs, Tregs, and MDSCs infiltrating the TME." (PMID 35685442, 2022). "In tumor immunity, KIF2C was significantly associated with CAFs, TAMs, Tregs and MDSCs infiltrates in TME." (PMID 35685442, 2022). "In summary, KIF2C was highly expressed in multiple tumor tissues and was significantly associated with poor prognosis." (PMID 35685442, 2022). "Higher expression levels of TBX15 and miR-152 were associated with decrease of tumor growth, lower expression of KIF2C, and more sensitivity to DOX treatment in both vivo and vitro." (PMID 34663310, 2021). "Our study presents solid experimental evidence that the mutated KIF2C gene is expressed and presented on the surface of tumor cells of the patient." (PMID 34099720, 2021). "Among the five hub genes, the altered CCNA2, DLGAP5, MAD2L1 and KIF2C were associated with tumor grade, and were significantly up-regulated in LUSC compared with other NSCLC, implicating crucial roles of them in LUSC progression." (PMID 32411535, 2020). "Among the five hub genes with prognostic values genes, four (CCNA2, DLGAP5, MAD2L1 and KIF2C) were associated with LUSC tumor grade." (PMID 32411535, 2020). "The result demonstrated that MAD2L1and KIF2C were significantly associated with patients age, ER and PR status, tumor stage and size; PLK1was related to ER and PR status, tumor stage and size." (PMID 29467930, 2018). "Higher KIF-2C expression was associated with significantly increased risks of higher pathologic tumor (pT) status (P=0.038) and poorer tumor differentiation (P=0.022)." (PMID 27563815, 2016). "Furthermore, high KIF2C expression was associated with an immunosuppressive tumor microenvironment characterized by immune exhaustion." (PMID 40292920, 2025). "In the context of TMM, the upregulation of KIF2C could be associated with its role in promoting cell proliferation and cell cycle progression, leading to enhanced tumor growth." (PMID 38763334, 2024). "Additionally, upregulated KIF2C was associated with high tumor staging (IV), shorter OS and poorer differentiation." (PMID 38344808, 2024). "We analyzed the correlation of KIF2C with expression, prognosis, tumor mutation burden (TMB), microsatellite instability (MSI), mismatch repairs (MMR), immune infiltration and anticancer drug sensitivity by R language.KIF2C was highly expressed in several tumors and correlated with poor prognosis." (PMID 35685442, 2022). "CCNA2, DLGAP5, MAD2L1, and KIF2C were significantly up-regulated compared to other subtypes, and associated with tumor stage in LUSC, suggesting that they might tightly be involved in progression and prognosis of LUSC." (PMID 32411535, 2020). "Moreover, our findings indicated that higher levels of KIF-2C in tumor tissues were associated with an advanced malignant phenotype because of patients’ higher pT status and poorer tumor differentiation." (PMID 27563815, 2016).
tumor (continued). "We found that in addition to the cell cycle, KIF2C expression was also significantly associated with complement and coagulation cascade, IL-17 signaling pathway, and cytokine-cytokine receptor interaction, suggesting that KIF2C is involved in tumor regulation of immunity." (PMID 35685442, 2022). "Prognostic validation in HCC cohorts revealed significant overexpression of these genes in tumours, with elevated Kif2c and Ccna2 predicting poor survival." (PMID 41323394, 2025). "Functional assays revealed KIF2C knockdown curtailed proliferation, invasion, and clonogenic growth, suggesting its tumor-promoting role downstream of taurine metabolism." (PMID 41341805, 2025). "Using the ssGSEA algorithm, we found that higher KIF2C expression correlated with decreased immune cell infiltration levels in the OS tumor microenvironment, resulting in an overall impairment of immune cell function." (PMID 40292920, 2025). "Specifically, Ccna2, Kif2c, and Racgap1 primarily promote tumor cell proliferation and division by regulating the cell cycle and mitotic processes." (PMID 41323394, 2025). "KIF2C, a member of the kinesin family, participates in multiple biological processes, including tumor invasion, metastasis, immune escape, and cell senescence." (PMID 40725496, 2025). "Specifically, high KIF2C expression correlated with greater tumour stage, lymph node metastasis, disease recurrence, and worse overall survival." (PMID 40002279, 2025). "We found a close relationship between high KIF2C expression and improved tumor purity in OS, coupled with lower immune and stromal scores." (PMID 40292920, 2025). "The apoptosis assay revealed that KIF2C inhibited cell apoptosis, enhancing the survival of tumor cells." (PMID 40292920, 2025). "Previous studies have revealed that Kif2c promotes tumor invasion and metastasis by inducing chromosomal instability through interference with chromosome segregation processes." (PMID 41323394, 2025). "Silencing KIF2C suppressed OS cell proliferation, migration, invasion, and in vivo tumor growth, while promoting apoptosis; conversely, overexpression of KIF2C had the opposite effect." (PMID 40292920, 2025). "Lastly, both S100A9 and KIF2C, as being an integral part of the tumor microenvironment, have been reported as suitable markers for evaluating immunotherapy response." (PMID 39268460, 2024). "Specifically, we observed 31 genes that were highly expressed and hypomethylated, including genes associated with tumor cell proliferation and migration, such as ATP1A1, EPCAM, TOP2A, and KIF2C." (PMID 38730618, 2024). "Numerous studies support KIF2C’s oncogenic potential showing that it is highly expressed in tumor cells from different origins and that the degree of de-differentiation of tumor cells depends on the expression level of KIF2C." (PMID 38344808, 2024). "In vivo xenograft nude mouse models verified that KIF2C was a critical gene for tumor growth in LUAD." (PMID 39309447, 2024). "KIF2C enhanced cell proliferation, invasion, and migration in vitro and increased tumor growth in vivo." (PMID 38344808, 2024). "In non-small cell lung cancer (NSCLC) tissues, the gene expression of KIF2C was found to be significantly upregulated compared to paired non-tumor samples in three independent RNA sequencing datasets." (PMID 38344808, 2024). "We demonstrated the effects of KIF2C on LUAD in vivo, by observing a considerable decrease in tumor growth following KIF2C knockdown in nude mice compared to the control group, which suggests that KIF2C is a critical gene for tumor growth in vivo in LUAD." (PMID 39309447, 2024). "Subsequent Kaplan-Meier (K-M) survival analysis illustrated that patients with higher KIF2C expression suffered a worse OS and DFS, in addition to poorer tumor differentiation and higher relapse risk." (PMID 38433242, 2024).
tumor (continued). "Based on immunohistochemical staining of malignant tissue sections, a high expression of KIF2C increased the incidence of a high pathologic tumor and poor tumor differentiation status in male patients, though not in female patients." (PMID 38344808, 2024). "At the same time, miR-186-3p can negatively regulate the expression of KIF2C, thereby exerting a tumor suppressor effect." (PMID 37142638, 2023). "According to the results, tumor tissues had significantly higher levels of KIF2C mRNA than normal tissues." (PMID 37142638, 2023). "ERCC6L, AHR and KIF2C downregulation were found to be potential mechanism of anti-tumor property of esketamine." (PMID 37968758, 2023). "The proliferation rate and the final tumor size of the overexpressed KIF2C group were undoubtedly larger than those of the other groups." (PMID 36900292, 2023). "The results of MCP-counter showed a decreased number of tumor-infiltrating immune cells, including monocytic lineage, myeloid dendritic cells and T cells in the high KIF2C expression group compared with the low expression group." (PMID 37717078, 2023). "Study has found that KIF2C participated in the modification of the cytoskeleton during cell invasion and migration, which are important steps in tumor cell proliferation." (PMID 37142638, 2023). "To determine the correlation between KIF2C and tumor microenvironment, we firstly compared the differences in immune scores, stromal scores, and ESTIMATE scores between the high and low KIF2C expression groups." (PMID 37016301, 2023). "In this study, the results very clearly demonstrate that the higher the expression level of KIF2C, the higher the degree of malignancy of the tumor." (PMID 36900292, 2023). "The mRNA expression levels of KIF2C in tumor samples and matched normal samples were investigated using the TIMER database." (PMID 37016301, 2023). "In order to assess the relationship between KIF2C expression levels and tumor microenvironment, we first compared the differences in ESTIMATE, Immune and Stromal score among the high and low KIF2C expression groups." (PMID 37717078, 2023). "Compared to the control group, the tumor volume of KIF2C-overexpressing mice was larger, and the tumorigenesis time was shorter." (PMID 36900292, 2023). "In THYM, KIF2C strongly correlated with CD8+ T cells with tumor suppressive effects and negatively correlated with CAFs, M2 macrophages, Tregs, and TIDE score, suggesting that KIF2C expression in THYM is a protective factor that predicts a better ICB response." (PMID 35685442, 2022). "KIF2C was shown to have a strong relationship with the tumor microenvironment (TME), infiltrating cells, and immune checkpoint genes." (PMID 35720323, 2022). "We divided the tumors into two groups, high and low expression, according to the median expression of KIF2C in various tumor types." (PMID 35685442, 2022). "By analyzing TCGA data, we found that KIF2C expression levels were generally high in 33 types of tumor tissues, consistent with the results of analysis of CCLE gene expression data." (PMID 35720323, 2022). "Kinesin superfamily member 2C (KIF2C) is an essential regulator of the cell cycle and its aberrant expression can promote tumor progression." (PMID 35685442, 2022). "We then analyzed the association between KIF2C expression and immune markers in KIRC, LGG, LIHC, and TYHM, and to reduce bias, we corrected the data according to tumor purity." (PMID 35685442, 2022). "Strikingly, in PCa, our findings showed that KIF2C expression was favorably connected with immunological and estimation scores but negatively correlated with tumor purity in PCa; the outcomes for other malignancies are given in a heat map." (PMID 35720323, 2022). "Clinical Proteomic Tumor Analysis Consortium analysis showed that the protein expression of KIF2C was higher in primary tissues of BRAC, OV, COAD, KIRC, UCEC, and LUAD compared with those in normal tissues." (PMID 35153749, 2021).
tumor (continued). "To investigate the role of the KIF2C in EC in vivo, we established a subcutaneous graft tumor model using Ishikawa cells in nude mice." (PMID 34650608, 2021). "Kinesin family member 2C (KIF2C) is known as an oncogenic gene to regulate tumor progression and metastasis." (PMID 35153749, 2021). "We found that tumor growth of the sh-KIF2C group was significantly decreased compared with that of the control group." (PMID 35153749, 2021). "Employing loss-of-function studies, we demonstrated that decreasing KIF2C expression inhibited cell proliferation, migration, and invasion in vitro and inhibited tumor growth in vivo, suggesting an oncogenic role of KIF2C during EC progression." (PMID 34650608, 2021). "The volume and number of tumor nodules were decreased in the mice injected with KIF2C-depleted SK-hep1 cell in comparison to the control group." (PMID 32748349, 2021). "The findings of our study indicate that KIF2C influences the prognosis of EC and as a target for the therapy of EC and correlated with tumor immune cell infiltration in EC." (PMID 34650608, 2021). "As expected, KIF2C expression was significantly increased in most tumor tissues compared with normal tissues, including TCGT and LAML." (PMID 35153749, 2021). "KIF2C overexpression can promote correct chromosome segregation in chromosomally unstable tumor cell lines." (PMID 30386706, 2018). "Specifically, after controlling for tumor differentiation, pT and pN status, pTNM stage, and surgical quality, male patients with high levels of KIF-2C expression had significantly worse OS and DFS compared with male patients with low expression." (PMID 27563815, 2016). "Only tumor differentiation (P=0.022) and pathologic tumor (pT) status (P=0.038) were significantly associated with KIF-2C expression, and higher levels of KIF-2C were associated with poorer tumor differentiation or higher pT status." (PMID 27563815, 2016). "KIF-2C was expressed in 99.5% of tumor cells, including 31.3%, 43.5%, and 24.8% that were weakly, moderately, and strongly positive." (PMID 27563815, 2016). "Prognosis was worse for male patients with high KIF-2C expression compared with patients with the same pathologic tumor-node-metastasis (pTNM) stage." (PMID 27563815, 2016). "In healthy adults, KIF-2C expression is limited to male germ cells, but high expression can be observed in tumor cells." (PMID 27563815, 2016). "Kaplan–Meier analysis of the entire cohort revealed that sex, tumor differentiation, pT status, pathologic node (pN) status, pathologic TNM (pTNM) stage, surgical quality, and KIF-2C expression were associated with OS and DFS (all P<0.05)." (PMID 27563815, 2016). "In summary, this study showed that KIF-2C expression in tumor tissues promises to serve as an independent prognostic marker for male, but not female, patients with operable ESCC." (PMID 27563815, 2016). "Based on these findings, KIF-2C expression in tumor tissues promises to serve as an independent prognostic marker for male, but not female, patients with operable ESCC." (PMID 27563815, 2016). "Multivariable regression analysis of male patients indicated that high levels of KIF-2C were independently associated with a significantly increased risk of ESCC-related death (HR=1.480, P=0.013) and tumor recurrence (HR=1.418, P=0.024)." (PMID 27563815, 2016). "Additionally, KIF2C was pinpointed as a potential mediator linking metabolic alterations to tumor aggressiveness, with implications for future therapeutic intervention." (PMID 41341805, 2025). "Based on these observations, we hypothesize that elevated KIF2C expression in OS plays a crucial role in driving tumor progression." (PMID 40292920, 2025). "Combined with the results of previous studies indicating that the WNT/β‐catenin pathway can induce CD8 T cell depletion, we believe that KIF2C is closely related to immune exhaustion in the OS tumor microenvironment, a process involving WNT/β‐catenin pathway activation." (PMID 40292920, 2025).
tumor (continued). "However, the exact role of KIF2C in OS, particularly in regulating tumor progression and metastasis, remains underexplored." (PMID 40292920, 2025). "Among the TRS genes, KIF2C was identified as a tumor-promoting factor." (PMID 41341805, 2025). "In vivo, reduced KIF2C expression led to a significant reduction in tumor volume and weight in mice, while overexpression of KIF2C promoted malignant proliferation and inhibited apoptosis in OS, highlighting the role of KIF2C in the malignant progression of OS." (PMID 40292920, 2025). "In LSCC, KIF2C was found to be a hub gene in two independent bioinformatic approaches using multiple comprehensive publicly available RNA expression datasets, but further investigations are required to decipher the clinicopathological impact of KIF2C’s expression in this tumor entity." (PMID 38344808, 2024). "These investigations could show that KIF2C modulates the proliferation, migration, metastasis and tumor growth in vitro and in a mouse model." (PMID 38344808, 2024). "The overexpression of KIF2C is very crucial to explore whether it can promote tumor proliferation and enhance the abilities of invasion and migration." (PMID 36900292, 2023). "Although KIF2C is substantially expressed in a number of tumor types, its exact mode of action is yet unknown in lung cancer." (PMID 37142638, 2023). "Eight weeks later, the samples of lung metastases were taken out, and it was observed with the naked eye that the lung surface of the sh-KIF2C group was smoother, and the number of tumor metastases was lower, while the lung surface of the KIF2C group was full of lesions." (PMID 36900292, 2023). "However, in both cell lines, the overexpression of KIF2C did significantly promote the proliferation of tumor cells." (PMID 36900292, 2023). "In addition, KIF2C was also connected to the degree of tumor differentiation, and the expression of KIF2C was significant in poorly differentiated tumors." (PMID 36900292, 2023). "The latest research has found that KIF2C, as a stemness related genes, may affect the efficacy of chemotherapy and immunotherapy by regulating the tumor microenvironment in LUAD21." (PMID 37142638, 2023). "Regarding tumor metastasis stage, KIF2C expression was higher in patients classified as M0 and M1." (PMID 35720323, 2022). "And EXT1 may affect tumor survival by activating the Wnt signaling pathway By PPI network analysis, we found that EXT1 was associated with KIF2C." (PMID 35685442, 2022). "The expression of KIF2C is significantly correlated with clinical and pathologic tumor features." (PMID 35720323, 2022). "However, in tumor cells, the regulation of KIF2C is disturbed and instead enhances mitotic defects and promotes tumor progression.Previous studies have shown that KIF2C is overexpressed in some tumors and promotes their progression." (PMID 35685442, 2022). "The expression of KIF2C mRNA was observed to be higher in tumor tissues." (PMID 35720323, 2022). "In addition, when 52 paired tumor samples were compared to adjacent normal samples, KIF2C expression was found to be significantly higher in PRAD." (PMID 35720323, 2022). "Nevertheless, the molecular mechanisms underlying the role of KIF2C in tumor development and progression have not been investigated." (PMID 32748349, 2021). "The ectopic expression of TBC1D7 was shown to reduce KIF2C-increased tumor volume and tumor weight." (PMID 32748349, 2021). "Based on its biological function, KIF2C has been suggested to have tumor-promoting properties." (PMID 35153749, 2021). "The increased transcriptional level of KIF2C was correlated with aggressive tumor behavior in EC, which reveals that KIF2C may play an essential role in most EC tumor development." (PMID 34650608, 2021). "Phosphorylation of S192 site could lead to the inhibition of KIF2C depolymerase activity and reduced directional migration and invasion of tumor cells." (PMID 33311452, 2020).